NPY (neuropeptide Y)
Diseases named in the same sentence as NPY in open-access papers (continued):
Sharing a sentence is not in itself a finding about the gene and the disease.
Anxiety (continued). "The increase in NPY expression may be also a response to the anxiogenic-like effects on stress response as the peptide is negatively correlated with anxiety symptoms." (PMID 25100947, 2014). "The DSS-induced behavioral syndrome comprises a reduction of locomotion and exploration, an apparent increase in anxiety and a decrease in social activity and is associated with enhanced expression of COX-2 in the hypothalamus and attenuated expression of BDNF, NPY, and MR in the hippocampus." (PMID 25414650, 2014). "In addition, SSRIs also affect various neuropeptide levels (e.g., neuropeptide Y, oxytocin, arginine vasopressin), which independently can modulate stress and anxiety levels." (PMID 23706039, 2013). "Moreover, in rats, the number of NPY-ir neurons in La and BL is correlated inversely with anxiety-like behavior, and lesion of NPY-ir neurons results in increased anxiety-like behavior." (PMID 22527118, 2013). "Meanwhile, NPY knockout rats show significant depression and anxiety-like behavior." (PMID 23468908, 2013). "Thus, a wealth of studies indicate a positive correlation between NPY levels and resilience to deleterious effects of stress, and suggest a potential pharmacotherapeutic target for effectively reducing anxiety and enhancing resilience to adversity and stress." (PMID 23422934, 2013). "NPY is involved in the cerebral regulation of food intake, cognition, anxiety, mood and stress resilience, and these implications are borne out by a distinct phenotype of NPY−/− mice." (PMID 23992467, 2013). "In conclusion, our findings suggest that 5-HT/NPY interactions contribute to the complicated network of intrinsic inhibitory circuits in the basolateral amygdala, a nodal structure for modulating anxiety-related behavior, emotional learning and memory formation." (PMID 22527118, 2013). "Thus, rats in a feeding state of anorexia were found to be similar to those in a mental state of anxiety because both animals were in a state of decreased NPY and increased AP-1 signaling." (PMID 24225225, 2013). "Consistent with this, anorexigenic peptides such as leptin and cholecystokinin have been reported to increase anxiety-like behavior, whereas the orexigenic peptide neuropeptide Y (an established target for ghrelin in the arcuate nucleus) reduces anxiety-like behavior." (PMID 23071554, 2012). "NPY is one of the most abundant neuropeptides in the central nervous system, and has been shown to have multiple functions, including regulation of feeding behavior, anxiety, addiction, bone density and memory retention." (PMID 20128895, 2010). "Furthermore, stimulation of NPY activity in this brain structure suppresses anxiety-like behavior and dependence-induced increases in alcohol drinking." (PMID 19881886, 2008). "For example, NPY has powerful anxiety-reducing effects in animals." (PMID 19881886, 2008). "Moreover, infusion of a molecule that can activate these signaling mechanisms or of NPY directly into the central amygdala reproduced the neurochemical and anxiety-reducing effects of alcohol." (PMID 23584814, 2008). "Additionally, the neuropeptide Y-CGRP ratio may play a role in anxiety and in the action of antipsychotic drugs." (PMID 40766923, 2025). "On the basis of the observed effects of peri-LCNPY activation on LCNE neuronal excitability, we next hypothesized that local NPY signaling could represent an endogenous mechanism responsible for the regulation of anxiety in novel and/or anxiogenic environments." (PMID 40700482, 2025). "Further interrogation of NPY or galanin signaling across NA neurons and potential compensatory effects in breathing through changes in metabolism or other autonomic function under stress or anxiety may yield notable insights." (PMID 39287624, 2024).
Anxiety (continued). "However, an animal experiment showed that no reduction in anxiety-related behavior and fear-learning behavior was observed in mice chronically overexpressed in NPY, possibly due to reduced NPY receptor reactivity caused by overexpression of NPY." (PMID 36339882, 2022). "We also investigated whether the reduced expression of social fear might partly be due to a reduced anxiety-like behavior, and showed that NPY exerted anxiolytic-like effects when administered into the DH, DLS, CeA and BLA, but not when administered into the MeA." (PMID 33918123, 2021). "It is well established that the GABA could elevate the synthesis of growth hormone, lower the level of cortisol and stress related enzyme and increase the neuropeptide Y; an amino-acid neuropeptide that serve to reduce the anxiety, stress and a regulation of feed intake and fat storage." (PMID 32882778, 2021). "Considering the hypothesis that a shift from anxiolytic to anxiogenic effects of NPY is promoted by DPPIV activity—inducing its rapid degradation and a switch in Y-receptor affinity—our findings of lowered DPPIV and unaltered NPY levels in anxiety patients seem somewhat contradictory." (PMID 34267682, 2021). "Thus, during hunger, NPY originating from arcuate AgRP/NPY neurons may not only increase food intake, but also suppress anxiety‐ and fear‐related behavior by Y2R‐mediated suppression of specific BNST afferents/efferents." (PMID 31271235, 2019). "However, the role of GABA release from NPY+ interneurons in adolescent anxiety is unclear." (PMID 30024942, 2018). "In summary, we observed enhancement of anxiety-like behavior (increased thigmotaxis in the open field and increased avoidance of open arms in the elevated plus maze), nest building, and social dominance following the miRNA silencing of Gad1 in NPY+ interneurons in adolescent mice." (PMID 30024942, 2018). "As epileptic patients often suffer from CNS disorders including anxiety and depression, among others, it should be noted that abnormal expression of NPY receptors may be the consequence of an integrated response of NPY system to comorbidity." (PMID 26943580, 2016). "Also, for individuals with altered NPYergic system, enhancing NPY levels and function may help to improve stress and anxiety regulation and to minimize the anxiogenic effects of CRH." (PMID 23422934, 2013). "Our morphological findings indicate that these stress- and anxiety-responsive serotonergic afferents may be in a position to influence the activity of NPY-ir interneurons and thus may modulate an important intrinsic anxiolytic inhibitory network of the La and BL." (PMID 22527118, 2013). "Thus, a deficiency in NPY signaling in the CeA may be involved in regulating both anxiety and alcohol-drinking behaviors and NPY system modifications can influence alcohol intake." (PMID 23584117, 2012). "Infusion of NPY into the central nucleus of the amygdala has been shown to normalize both anxiety behaviors and alcohol intake, suggesting that NPY might work by modulating anxiety responses." (PMID 23584116, 2012). "Neuropeptide Y (NPY), a 36 amino acid peptide, is one of the most abundant peptides in the central and peripheral nervous system of mammals, involved in numerous (patho)physiological functions such as food intake, blood pressure, regulation of hormone secretion, anxiety and memory." (PMID 23236424, 2012). "Stressful experiences recruit peri-LCNPY neurons, leading to local NPY release in vivo, whereas enhanced peri-LCNPY neuronal activity curbs anxiety after stress." (PMID 40700482, 2025). "The NPY peptide, expressed in the CeA and BLA, is involved in emotional eating, as it has both an anti-anxiety effect and one of the strongest known feeding-inducing properties." (PMID 40431402, 2025). "Gene expression analysis of feeding-related genes (AgRP, NPY, OXT) and those involved in regulating stress and anxiety (DOR and MC3R) were differentially regulated in the VPA rats." (PMID 40004532, 2025).
Anxiety (continued). "Neuropeptide Y (NPY) plays a key role in stress regulation, exerting anxiety-reducing effects and supporting adaptive responses to adversity." (PMID 41300812, 2025). "Other rat-based studies cite a more complex role in anxiety and depression through suppression of corticotropin-releasing factor (CRF) expression and stimulation of neuropeptide Y (NPY) expression in the hypothalamus." (PMID 41002721, 2025). "Neuropeptide Y (NPY) and galanin have been shown to co-exist in LC NA neurons and are involved in regulating energy metabolism, stress, or anxiety." (PMID 39287624, 2024). "Neurotransmitters such as gamma-aminobutyric acid (GABA), glutamate, and monoamines (serotonin, norepinephrine, dopamine), along with neuropeptides like NPY and corticotropin-releasing factor (CRF), regulate anxiety within this network." (PMID 39275174, 2024). "In contrast, in 2018, we found upregulated NPY levels after SAH, related to poorer hrQoL (as to psychological health, depression, anxiety and nutrition disorder)." (PMID 38425753, 2023). "Abnormal expression of brain-gut peptides, like ghrelin, NPY, CCK, PYY, and GRP, in the peripheral and central systems can lead to depression, anxiety, gastrointestinal diseases, and metabolic disorders." (PMID 37511879, 2023). "To determine the role of MHb NPY in the development of allodynia, photophobia, and anxiety under GTN condition, we performed microinjection of NPY into the bilateral MHb immediately before GTN injection." (PMID 37231359, 2023). "Thus, NPY might reduce psychological distress and exerts anxiety-relieving effects." (PMID 36579027, 2022). "A recent study reported significant correlations between CGRP, NKA, NPY, NTS, and anxiety-like behavior in rats." (PMID 36004833, 2022). "Specifically, female rats with anxiety-like behavior had increased BDNF concentration in the HIP and cortex and decreased neuropeptide Y as well as parvalbumin interneurons in the CA1 region." (PMID 36159923, 2022). "The importance of neuropeptide Y for the pathology of this disease became evident in mice with a neuropeptide Y (NPY) gene deletion, as these mice exhibited high anxiety levels and a high alcohol-drinking phenotype." (PMID 36263121, 2022). "ICAM-1 deletion in TBI improves sensorimotor, depression, and anxiety-like behavior with significant upregulation of norepinephrine (NE), dopamine (DA) D1 receptor (DAD1R), serotonin (5-HT)1AR, and neuropeptide Y (NPY)." (PMID 34135004, 2021). "Recently, we used NPY-Cre mice and AAV injection to specifically ablate or activate NAc NPY neurons to their role in modulating anxiety behavior." (PMID 34298907, 2021). "Zebrafish also possess a Y1 receptor gene in their genomes, and a co-ICV injection of NPY and mammalian Y1 antagonist BIBP-3226 suppresses fish Y1 receptor functioning, such as suppression of anxiety in black-white test." (PMID 32246073, 2020). "Neuropeptide Y inhibits the biological actions of CRF and is involved in the termination of the stress and anxiety response." (PMID 33574739, 2020). "In men we observed a positive correlation of PP with anxiety scores (GAD-7: r = 0.41, p = 0.007) and with age (r = 0.49, p = 0.001) on admission while NPY negatively correlated with age (r = -0.38, p = 0.01)." (PMID 33192409, 2020). "We analyzed the modulation of calcitonin gene-related peptide (CGRP; exerting anxiogenic effects in BNST), neuropeptide Y (NPY; exerting mainly anxiolytic effects), and microglia activation (neuroinflammation marker, thought to increase anxiety)." (PMID 31114482, 2019). "Rats pretreated with intranasal NPY before single prolonged stress (SPS) exposure show less depressive-like and anxiety-like behavior." (PMID 30186127, 2018). "In contrast, transgenic rats overexpressing NPY in the CA1 and CA2 areas of the hippocampus are resistant to stress-induced anxiety-like behavior in the elevated plus maze and in the Vogel conflict test." (PMID 30131681, 2018).
Anxiety (continued). "For example, neuropeptide Y (NPY) and its receptors play a key role in linking information from the gut (e.g., via pancreatic polypeptide) to food intake, energy homeostasis, anxiety and mood." (PMID 30210279, 2018). "Additionally, Y2 receptor knockout showed a low-anxiety phenotype in the elevated plus maze and open field tests, suggesting that in addition to limiting NPY-release, the Y2 receptor may counterbalance anxiolytic effects of NPY." (PMID 28824541, 2017). "Moreover, in Sprague-Dawley rats and C57BL/6 mice, maternal separation and social isolation induce an upregulation of orexigenic neuropeptide Y in the hypothalamic region that is related to increased anxiety, and could lead to hyperphagia and consequently promote weight gain." (PMID 27611197, 2016). "Neuropeptide Y (NPY) is the most abundant neuropeptide in the mammalian brain and modulates various mechanisms, such as appetite, anxiety, circadian rhythm, memory and blood pressure." (PMID 25624911, 2015). "On the other hand, NPY and SST themselves are powerful modulators of anxiety-related behavior and have anxiolytic properties when administered to the amygdala." (PMID 24478650, 2014). "Notably, feeding-related genes (AgRP, NPY, OXT) and those involved in regulating stress and anxiety (DOR and MC3R) were differentially regulated in the VPA rats." (PMID 40004532, 2025). "Outcomes included anxiety (HAMA), depression (Hamilton Depression Scale [HAMD]), sleep quality (PSQI), polysomnography (PSG), and neurotransmitter levels (norepinephrine [NE], serotonin [5-HT], neuropeptide Y [NPY])." (PMID 40401023, 2025). "Previous data have revealed the increased incidence of depression and anxiety in patients with OSAS, suggesting that NPY may also have a role in mental and psychological disorders in patients with OSAS, which requires further exploration." (PMID 40989139, 2025). "Furthermore, site-directed infusion of NPY and a Y1 receptor agonist alleviated GTN-induced allodynia and anxiety-like behaviors." (PMID 37231359, 2023). "A reduction in NPY signaling in the amygdala leads to negative behavioral consequences, such as anxiety." (PMID 37149657, 2023). "Increase in anxiety like behavior, increase in Bacteroidetes, decrease in Firmicutes/Bacteroidetes ratio, increase in intestinal levels of IL-6, TNF-α, 5-HT, and decrease in corticotropin-releasing hormone, BDNF, and neuropeptide Y in the brain." (PMID 37324381, 2023). "A large literature has shown that various neuropeptides, including corticotropin-releasing factor (CRF), cholecystokinin (CCK), arginine vasopressin (AVP), oxytocin, orexin, neuropeptide Y (NPY), neuropeptide S (NPS), galanin, and neurokinins, such as substance P, affect anxiety-related behaviors." (PMID 36623804, 2023). "Taken together, NPY in the MHb attenuated GTN-induced allodynia and anxiety without affecting photophobia, whereas microinjection of NPY in the VEH mice led to an increase in anxiety-like behavior." (PMID 37231359, 2023). "In addition, we also analyzed the effects on the mRNA expression of other signaling systems related to anxiety and stress (e.g., CRH and neuropeptide Y (NPY)) in the amygdala of young male adult rats." (PMID 35327395, 2022). "Furthermore, it has been shown that NPY via NPY1R activation suppresses the corticotropin-releasing factor (CRF) and modulates GABAergic pathways in the CeA to regulate anxiety and alcohol-related behaviors." (PMID 36089615, 2022). "Instead, NPY slightly affected tension-anxiety scores in the non-finisher group at D2 by increasing them." (PMID 36579027, 2022). "The primary outcome was fatigue (Multi-dimensional Fatigue Inventory 20 [MFI-20]), and secondary outcomes were sleep quality (Pittsburgh Sleep Quality Index [PSQI]), anxiety, depression (Hospital Anxiety and Depression Scale [HADS]), and changes in the Neuropeptide Y (NPY) of peripheral blood." (PMID 35847786, 2022).
Anxiety (continued). "High prenatal androgen excess may lead to dysregulation of neuropeptide Y, parvalbumin, and BDNF, leading to increased anxiety-like behavior." (PMID 36159923, 2022). "Addressing each of these, there is evidence that the NPY system affects anxiety; the PP Y4 receptor has been shown to modulate anxiety in rodents; and multiple GLP-1 receptor agonists have been used to address anxiety in animal models." (PMID 33643090, 2021). "In the present study, the higher levels of NPY in the BNST of resilient rats may be neuroprotective against harmful stressful stimuli and prevent increased anxiety and ethanol consumption." (PMID 34975380, 2021). "While anxiety, depression, PTSD, and ADHD are associated with changes in the functional connectivity of intrinsic brain networks, how NPY affects functional connectivity has not been studied." (PMID 34867217, 2021). "A recent Chinese study showed that the level of NPY in peripheral blood of epileptic children was significantly increased and was positively correlated with NIHSS score and Hamilton Anxiety (HAMA) scores, suggesting that NPY is involved in the onset of epilepsy." (PMID 34422139, 2021). "In this study, in contrast to depressive behavior, sub-therapeutic dose of NPY was not sufficient to prevent the development of SPS-elicited anxiety-like behavior on any of the EPM measures or social impairments." (PMID 34566592, 2021). "These partly differential effects of NPY on anxiety (i.e., non-social anxiety) and social anxiety suggest that distinct brain regions and receptor subtypes mediate the effects of NPY on social versus non-social anxiety." (PMID 34576305, 2021). "There have been evidences suggesting that the somatostatin (SST) and neuropeptide-Y (NPY) expression in the amygdalar neurons plays a key role in the regulations of fear and stress responses as well as anxiety which manifest over the entire trajectory of schizophrenia." (PMID 32765318, 2020). "Surprisingly, overexpression of NPY in cells that regularly express NPY in mice did not lead to the expected reduction in anxiety-like behavior." (PMID 33123166, 2020). "Therefore, in the present study we investigated the relationship between circulating levels of the members of the NPY family (NPY, PYY, PP) and psychometrically evaluated anxiety, depressiveness and perceived stress in obese psychosomatic patients." (PMID 33192409, 2020). "Several reports have suggested that changes in fish behaviour in the mirror test represent negative social interactions, including aggression and anxiety, which are related to mammalian NPY functions." (PMID 32246073, 2020). "At the same doses effective in males, intranasal NPY did not prevent the development of depressive-like or anxiety behavior after exposure of females to stress." (PMID 32867327, 2020). "Although wild and NPY-KO zebrafish showed no abnormal behaviour during the acclimation, NPY-KO exhibited anxiety with the uncovering of white area after the removal of the wall between black and white area." (PMID 32246073, 2020). "Lastly, improvement of anxiety scores did not lead to significant changes in plasma NPY levels (p > 0.050)." (PMID 33192409, 2020). "Intranasal NPY at the doses shown to be effective in males, did not prevent development of depressive or anxiety-like behavior or molecular changes in the LC." (PMID 30804766, 2019). "Specific subtypes of NPY+ cell types are found to be stress-sensitive, which lead to impairment of endogenous NPY release and alteration in CA1 circuit function which altogether potentially contribute to heightened anxiety." (PMID 31281833, 2019). "In addition, CeA neurons can express several neuropeptides that play important roles in fear and anxiety behaviors such as CRF, enkephalins, dynorphins, somatostatin and NPY." (PMID 31167849, 2019).